PIK3R3 (phosphoinositide-3-kinase regulatory subunit 3)
Diseases named in the same sentence as PIK3R3 in open-access papers (continued):
Sharing a sentence is not in itself a finding about the gene and the disease.
tumor (continued). "Analysis of PIK3R1, PIK3R3 and PIK3CA mRNA expression in these datasets revealed that PIK3R1 was significantly down-regulated in PCa tumours relative to normal tissue in 9 of the 10 studies." (PMID 26501081, 2015). "We found that expression of PIK3R1, PIK3R3, and AKT3 significantly enhanced 6.27-, 9.78-, and 4.53-fold respectively in tumor tissues in comparison with arachnoidal tissue by qRT-PCR." (PMID 23285163, 2012). "Furthermore, miR-193a-5p suppresses LC metastasis by targeting ERBB4/PIK3R3/mTOR/S6K2, and this tumor suppressor was upregulated in males but downregulated in females." (PMID 38245882, 2024). "As a regulator subunit of class I PI3K complex, PIK3R3 has been suggested to play pivotal roles in different physiological and pathologic processes including cell proliferation, inflammation, epithelial-mesenchymal transition (EMT) and tumor growth." (PMID 38618952, 2024). "We found that PIK3R3 upregulated the expression of CDKN1C, downregulated the expression of SMC1A, and activated Akt signaling, thereby promoting HCC cell proliferation and tumor growth." (PMID 37212524, 2023). "However, the mechanism by which PIK3R3, ITGB8, TrkB, and CACNA1D induce cell autophagy and inhibit tumor growth remains to be elucidated." (PMID 36386893, 2022). "Based on the in vitro transcriptome analysis and validation of “cytokine-cytokine receptor interaction,” “PI3K-Akt signaling pathway” and “MAPK signaling pathway,” we measured the relative protein expression of TGFB2, INHBB, PIK3R3, ITGB8, NTRK, and CACNA1D in tumor tissue." (PMID 36386893, 2022). "PIK3R3 was down-regulated in SKOV3 cells transfected with si-PIK3R3 accompanied with the down-regulation of Twist and Rac1, which suggests Twist and Rac1 may mediate changes in PIK3R3 expression and affecting EMT in tumor cells." (PMID 30823895, 2019). "PIK3R3, a positive regulator of PI3K signaling, has recently been shown to be tumor-promoting in other cancers, while PTEN, a negative regulator of this pathway, is an established tumor suppressor." (PMID 25603314, 2015). "A number of these genes (including PIK3R3, a member of the PI3K pathway, and PKLR, an isoform of pyruvate kinase) showed exceptionally strong co-expression with HNF4A in normal samples, only to have this co-expression abrogated in tumor samples." (PMID 25961905, 2015). "Moreover, DK1 also enhanced the expression of several other tumor suppressor genes that are related to this pathway such as FOXO, TP73, CDKN1A, Caspase, CYCS, and GADD45A while impeded the expression of other proto-oncogenes namely PIK3R3, BCL-2, IGFBP2, HGF, and FGF." (PMID 34204873, 2021). "Moreover, in terms of PIK3R3, RNASE7, and TNFRSF12A, similar results have been obtained in other researches, indicating that these genes might be engaged in immune-related pathways and promote tumor progression." (PMID 33193693, 2020).
cancer (58 papers, 2009 to 2025). A tumor composed of atypical neoplastic, often pleomorphic cells that invade other tissues. "Treatment of A375 cells with TRE in our study resulted in an increased relative expression of the PIK3R3 gene, which is closely linked to cancer cell migration." (PMID 41170188, 2025). "This includes pairs of hsa-miR-23b-3p and NACC1, a cancer-related transcription regulator, hsa-miR-23b-3p and PIK3R3, as well as hsa-miR-134-5p and INA gene that encodes neuronal intermediate filament involved in pituitary tumorigenesis." (PMID 32413978, 2020). "PIK3R3 (p55γ) is one of five regulatory phosphoinositide-3-kinase subunits active in a variety of growth-promoting responses implicated in human cancer." (PMID 25814554, 2015). "We thus used genetic and bioinformatic approaches to examine PIK3R3 expression and function in GC, the second leading cause of cancer mortality world-wide and highly prevalent among Asians." (PMID 22876838, 2012). "The SOCS family of genes, which are important regulators of PIK3R3/STAT3 signaling, can be used to develop molecularly targeted drugs to inhibit PIK3R3/STAT3 signaling in a variety of cancers with unique modes of action." (PMID 39307915, 2024). "According to previous research, PIK3R3 works as a crucial regulator of FoxO pathway and promotes the progress of malignant tumors." (PMID 39692250, 2024). "Several studies explored the upstream molecules of PIK3R3, especially in a series of microRNAs, and the roles of PIK3R3 in cancers." (PMID 37212524, 2023). "The largest re-ranked pan-cancer feature importance is attributed to the gene PIK3R3 (Phosphoinositide-3-Kinase Regulatory Subunit 3)." (PMID 35106465, 2022). "KEGG enrichment analysis revealed that the interacting partners of PIK3R3 are involved in the ErbB signaling pathway, proteoglycans in cancer, FoxO, prolactin, chemokine, and insulin signaling pathways." (PMID 35761259, 2022). "Functional analyses indicated that circ_0061395 inactivates miR-877-5p and contributes to cancer progression by positively modulating the expression of phosphoinositide-3-kinase regulatory subunit 3 (PIK3R3)." (PMID 35055115, 2022). "The negative regulation of PIK3R3 by BPTF was lost from normal to cancer, which was in accordance with the over-expression of PIK3R3 in cancer." (PMID 35421923, 2022). "PIK3R3 is an enzyme that participates in multiple cancer-related signaling pathways, most importantly PI3K-AKT-mTOR signaling." (PMID 35106465, 2022). "the PI3K regulatory subunits PIK3R2/p85beta and PIK3R3/p55gamma, are frequently overexpressed in various cancers." (PMID 35459184, 2022). "Our finding provides new knowledge of the mechanism involving PIK3R3 of miR-513b-5p-mediated cancer progression." (PMID 34120890, 2021). "It has been reported that miR-601 is a potential cancer inhibitor by repressing PIK3R3 in HCC cells." (PMID 34120890, 2021). "Our correlation-based target predictions indicate that regulatory unit of PI3K i.e., PIK3R3 and cancer-driving transcription factor NACC1 are probable targets of hsa-miR-23b." (PMID 32413978, 2020). "The 8-mRNAsi based prognostic model in our signatures includes RGS16, LYVE1, hnRNPC, ANP32A, AIMP1, ZNF66, PIK3R3, and MAP2K7, in which several genes have been reported to be linked with stemness features or be involved in cancer progression." (PMID 33329703, 2020). "It has also been found to act as a cancer-suppressive miRNA by targeting important oncogenes, such as PIK3R3, TRIB2 and Bax." (PMID 28114950, 2017). "Of note, PI3K pathway-independent mechanisms have previously been reported for PIK3R3 in other cancers." (PMID 25603314, 2015). "Although PIK3R3 is overexpressed in several cancers, little is known about the expression and functional role of PIK3R3 in GC." (PMID 22876838, 2012).
cancer (continued). "The role of PIK3R3 in several malignant tumors has been confirmed." (PMID 39692250, 2024). "The abnormally activated PIK3R3/STAT3 signaling pathway is critical for many cancers." (PMID 39307915, 2024). "PIK3R3 acts as an oncogene of various cancers, containing glioma, lung cancer, and gastric cancer." (PMID 34120890, 2021). "Among these downstream effectors, there are other molecules targeted by miR-193a-3p or miR-193a-5p: KRAS, a target of miR-193a-3p, and PIK3R3 and mTOR, targets of miR-193a-5p, which are all proteins stimulating proliferation, cell cycle progression, and cell survival in cancer cells." (PMID 32867069, 2020). "Using binding assays, protein complementation and phenotypic readouts to characterize the pY-dependent interactions of TSPAN2 (tetraspanin 2) and GRB2 or PIK3R3 (p55γ), we exemplarily provide evidence that the two pY-dependent PPIs dictate cellular cancer phenotypes." (PMID 25814554, 2015). "The hypothesis is that conditional pY-dependent interactions with different adaptor proteins, GRB2 or PIK3R3, respectively, may be altered in cancer, suggesting further investigation of TSPAN2 and its interactions in the transition of cells to abnormal growth." (PMID 25814554, 2015). "Taken together, these results suggest an oncogenic role for PIK3R3 in these cancers." (PMID 22876838, 2012). "Furthermore, the overexpression of PIK3R3 has been reported to be an oncogenic mechanism that promotes proliferation, metastasis, and resistance to apoptosis and chemotherapy in specific types of cancer." (PMID 39156764, 2024). "Meanwhile, PIK3R3 may be just one of the downstream targets of PIK3R3 in the modulation of cancer development, more potential factors response to miR-513b-5p-regulated cancer progression need to be explored in other investigations." (PMID 34120890, 2021). "Additionally, PIK3R3 is overexpressed in some cancers and has been reported to act as an oncogene." (PMID 33317596, 2020). "PIK3R3, part of the PI3K regulatory domain, is upregulated in various cancers, playing a crucial role in tumorigenesis, cell proliferation, and metastasis." (PMID 39668833, 2024). "As PIK3R3 is a member of the PI3K family, the aberrant activation of PI3K signaling is a common oncogenic event and triggers the activation of Akt in cancer." (PMID 37212524, 2023). "The subnetworks of ATF4, PIK3R1, and PIK3R3 filtered out from our study have been also shown to participate in TNF signaling pathway, since these hub genes involve immune regulation in cancer and AR disease." (PMID 37430199, 2023). "Phosphoinositide‐3‐kinase regulatory subunit 3 (PIK3R3) also called p55PIK, a part of the PI3K regulatory domain, is upregulated in various cancers and plays an important role in tumorigenesis, cell proliferation, and metastasis." (PMID 37212524, 2023). "Several of these specialized TME microenvironments are enriched by the pan-cancer survival network, for example HIF1A signaling (p = 4.27 × 10−6; FGF2, IGF2, MMP1, MMP14, MMP3, PIK3R3, SERPINE1, TGFB1)." (PMID 35106465, 2022). "MZF1 is also central for the activation of the expression of Phosphoinositide -3-Kinase Regulatory Subunit 3 Gamma (PIK3R3), which is a regulatory subunit of PI3 kinase (PI3K) needed for PI3K signaling and is important for cancer cell proliferation." (PMID 31963147, 2020). "FZD8, plasminogen activator, urokinase receptor, ITGA2, WNT2B, TIMP3, WNT5B, FGF5, heparanase, HBEGF and WNT3A were up-regulated in the proteoglycan pathways in cancer, whereas WNT10A, PIK3R3, IGF2 were down-regulated." (PMID 30482199, 2018).
cancer (continued). "Among these, the mRNA levels of PIK3R1 and CTNNB1 were increased more than 2-fold, and those of PIK3R3, PIK3CA and AKT3 were increased 1.6- to 1.9-fold after co-culture with cancer cells." (PMID 28173828, 2017). "Correspondingly, the marker genes, except PIK3R3 and CYP26B1, revealed elevated transcriptional enrichment scores in at least eight different cancer entities compared to healthy tissue shown by pan‐cancer expression analysis using the TNMplot web tool, emphasizing their general role in cancer." (PMID 39825568, 2025). "Moreover, ZSTK474 potentially hinders cancer progression by disrupting the PI3K/Akt pathway, resulting in G0/G1 cell cycle arrest primarily through targeting PIK3R3." (PMID 39466763, 2024). "PIK3R3, a PI3K regulatory domain P85 gene family member, is crucial for activating downstream signaling pathways through phosphorylated Akt, facilitating cellular processes such as survival, epithelial-mesenchymal transition, and cancer stem cell generation." (PMID 39466763, 2024). "Another very prominent pathway in cancer is ERK/MAPK signaling (p = 3.47 × 10−2; ESR1, FYN, ITGA3, PIK3R3, PLA2G4A, PLA2G5, RPS6KA5), which is the core of the signaling network involved in regulating cell growth, development, and division and a target of many cancer therapeutics." (PMID 35106465, 2022). "Previous studies confirmed that PIK3R3 could regulate the AKT/mTOR pathway, promoting cancer progression." (PMID 34961815, 2021). "PIK3R3 (p55γ subunit) is a regulatory subunit forming heterodimers with class IA p110α catalytic subunit (PIK3CA), the most studied catalytic subunit in cancer." (PMID 29682174, 2018). "For example, PIK3R3 (Entrez ID: 8503) is correlated with the prognostic risks of cancer patients in none of the 400 resamples, but it is identified by our method." (PMID 28615526, 2017). "In addition, PTK2 protein tyrosine kinase 2 (PTK2), phosphatidylinositol 3-kinase regulatory subunit gamma (PIK3R3), and phosphatidylinositol-4,5-bisphosphate 3-kinase catalytic subunit delta (PIK3CD) are shown to be related to pathways in cancer (KEGG ID: map 05200)." (PMID 30255812, 2018).
PIK3R3 also shares sentences with these, for which no sentence is quoted: infection (3 papers); diabetes (2); metastatic colorectal cancer (2); neurological disorder (2); oral squamous cell carcinoma (2); pancreatic cancer (2); asthma (1); ataxia telangiectasia (1); atrial septal defect (1); autoimmune disease (1); brain tumors (1); central neurocytoma (1); clear cell renal cell carcinomas (1); colorectal tumor (1); COVID-19 (1); cystadenocarcinoma (1); endometrial cancer (1); endometrioid carcinoma (1); esophageal squamous cell carcinoma (1); HCMV infection (1); hematologic malignancies (1); Hypergonadotropic hypogonadism (1); hypothyroidism (1); leishmaniasis (1); leukemia (1); lung adenocarcinoma (1); lymphoma (1); metastatic tumors (1); neonatal diabetes mellitus (1); neuroblastoma (1).
A further 5 diseases each share a sentence with PIK3R3 in 1 paper.